TERT (telomerase reverse transcriptase)
Diseases named in the same sentence as TERT in open-access papers (continued):
Sharing a sentence is not in itself a finding about the gene and the disease.
liver cancer (continued). "For example, integration events in the TERT gene, which encodes the catalytic subunit of telomerase, have been associated with increased expression of TERT in liver cancer samples, suggesting a direct link between viral integration and the activation of oncogenic pathways." (PMID 39764440, 2024). "Previous report indicated that TERT promoter mutations in tissue of cirrhosis correlate with the rate of hepatocarcinogenesis, with mutations identified in 6% of low grade dysplastic nodules, 19% of high grade dysplastic nodules, and 61% of early liver cancer." (PMID 35306637, 2022). "TERT promoter mutation is the most frequent genetic alteration in liver cancer." (PMID 35306637, 2022). "To address whether MEG3 inhibits the growth of liver cancer stem cells and is associated with TERT or TRF2, we constructed related cell lines and then performed rescue experiments." (PMID 33256840, 2020). "Only two studies evaluated the rs2853669 polymorphism and TERT promoter mutations in liver cancer." (PMID 28529542, 2017). "TERT promoter mutations have been rarely found in liver cancer displaying biliary phenotype." (PMID 27276713, 2016). "Considering the high specificity and the earliness of TERT promoter mutations in liver cancer, we hypothesize their use as reliable biomarkers of HCC development in cirrhotic patients." (PMID 27276713, 2016). "The combination of rs2853669 polymorphism and somatic TERT promoter mutations has reported to further increase TERT transcription levels and to be associated with higher risk of death and cancer recurrence in liver cancer patients." (PMID 27276713, 2016). "Further analysis indicated that TERT promoter mutations were more frequent in men (P = 0.026, χ2-test) and in patients with older age (P = 0.012, unpaired student's t test), poor tumor differentiation (P = 0.028, χ2-test) and advanced Barcelona Clinic Liver Cancer (BCLC) stage (P = 0.038, χ2-test)." (PMID 28460432, 2017). "Nevertheless, the present study demonstrates that aberrant upregulation of TERT promotes carcinogenesis in the progression of chronic hepatitis and liver cancer by enhancing inflammatory responses and regulating cell proliferation." (PMID 40213897, 2025). "TERT was positively correlated only in testicular and liver cancers, and negatively in rectal cancer." (PMID 40548474, 2025). "The Liver Cancer Model Repository database was used for screening potential drugs to selectively suppress the growth of TERT promoter mutant HCC cells." (PMID 38769666, 2024). "In addition, the genetic landscape of liver cancer, characterized by nodule-in-nodule feature for the presence of the inner hypervascular tissue surrounded by hypovascular transformed hepatocytes, showed that the two components shared many clonal genetic events, including TERT promoter mutations." (PMID 38033865, 2023). "Namely, in predicting NAFLD-related liver cancer, kappa coefficients were 0.528, 0.389, and 0.024 in TERT C228T, PIVKAII positivity, and AFP positivity, respectively." (PMID 35306637, 2022). "The multivariate analysis that included these factors identified vp (presence; OR 2.472, p = 0.037) and fibrosis stage (0, 1, 2; OR 3.774, p = 0.003) as significant and independent determinants of TERT C228T-positive liver cancer." (PMID 35306637, 2022).
liver cancer (continued). "The univariate analysis identified 2 parameters that tended to be or were significantly correlated with TERT C228T-positive liver cancer: body mass index (≥ 25.0 kg/m2, p = 0.047) and etiology (FLD vs. HBV; p = 0.009)." (PMID 35306637, 2022). "The multivariate analysis included these factors and identified etiology (FLD vs. HBV; OR 2.346, p = 0.010) as a significant and independent determinant of TERT C228T-positive liver cancer." (PMID 35306637, 2022). "The univariate analysis identified 2 parameters that tended to be or were significantly correlated with TERT C228T-positive liver cancer: vp (presence, p = 0.097) and fibrosis stage (0, 1, 2; p = 0.047)." (PMID 35306637, 2022). "We detected multiple genomic HBV integrations in two distinct types of liver cancer, with recurrent events at TERT, ZMAT4, MET, ANKFN1, PLXNB2 in ICC, and TERT, ALKBH5 in CHC." (PMID 36123506, 2022). "Here, we review recent findings regarding the interplay between TERT and β-catenin in order to better understand their role in liver cancer." (PMID 34439356, 2021). "Analysis of the TCGA database for TERT gene variations in liver cancer patients revealed that TERT gene amplification occurred in about 4% (23/587) of the liver cancer patients." (PMID 33239622, 2020). "Strikingly, our study also found that although MEG3 inhibited the growth of human liver cancer stem cells, the excess of telomerase reverse transcriptase TERT abolished the tumor suppressor function of MEG3." (PMID 33256840, 2020). "Our study suggests that MEG3 promotes the expression of TERRA and thus enhances the binding of TERRA to TERT, competitively inhibits the interaction of TERC with TERT, and ultimately inhibits telomerase activity in human liver cancer stem cells." (PMID 33256840, 2020). "Collectively, these results suggest that excessive TERT or TRF2 abrogates the inhibitory effect of MEG3 on the growth of human liver cancer stem cells." (PMID 33256840, 2020). "At the same time, MEG3 inhibits telomerase activity in human liver cancer stem cells by reducing the binding of TERT to TERC." (PMID 33256840, 2020). "In contrast, the mRNA level of TERT was upregulated in over 55% (338/587) of the liver cancer patients, suggesting that the expression of TERT was mainly regulated on the transcription level." (PMID 33239622, 2020). "The most notable example has been the identification of hot spot activating mutations in the promoter region of telomerase reverse transcriptase (TERT) gene in about 85% of human tumors, including liver cancer." (PMID 28529542, 2017). "For the liver cancer datasets, BatVI uncovered novel integrations to two important genes TERT and MLL4, which were missed by previous studies." (PMID 28361674, 2017). "Pu and colleagues found that H19 together with another lncRNA CUDR promotes liver cancer stem cell growth through upregulating TERT and C-Myc." (PMID 26989025, 2016). "For example, CUDR increased the exprseeion of HULC, β-Catenin, TERT and C-myc in human liver cancer stem cell." (PMID 27167190, 2016). "Ultimately, excessive TERT and C-myc lead to liver cancer stem cell and hepatocyte-like stem cell malignant proliferation." (PMID 26513297, 2015). "Notably, APC‐derived mutations were predominantly observed in colorectal cancer (18.6%, 11/59), while TERT promoter and CTNNB1 mutations were most found in liver cancer, with detection rates of 34.5% (10/29) and 24.1% (7/29), respectively." (PMID 39748775, 2025). "The impact of TERT on liver cancer is speculated to be due to the integration of hepatitis B virus affecting the stability of chromosomes." (PMID 38704528, 2024).
liver cancer (continued). "Thus, the purpose of the present retrospective study was to determine the clinical and histopathological factors associated with TERT C228T in serum samples, as well as to investigate the useful marker for the diagnosis of FLD-related liver cancer." (PMID 35306637, 2022). "New strategies to target telomerase in liver cancer are being studied in vivo and in vitro and include small molecules inhibiting TERT enzymes, antisense oligonucleotides and molecules that stabilize the DNA G-quadruplex or block telomerase access to telomeres." (PMID 36358677, 2022). "This makes TERT a specifically attractive target of therapeutic vaccines against liver cancer." (PMID 34067686, 2021). "We used TERT promoter mutations and miR-122 in the combination with AFP in the predictive models based on the evidence on clinical relevance of these biomarkers in the association with liver cancer." (PMID 32424223, 2020). "We found that many liver cancers had cycles of templated insertions that affect TERT." (PMID 32025012, 2020). "Integration events at TERT were found to recur in five different liver cancer samples." (PMID 32025001, 2020). "Furthermore, MEG3 reduces the binding of TERC to TERT, thereby further inhibiting the activity of telomerase in human liver cancer stem cells." (PMID 33256840, 2020). "It was reported that LINC-ROR promote liver cancer stem cell growth by upregulating TERT and C-MYC." (PMID 31890219, 2019). "TERT gene abnormalities were very frequently observed in all these three HCC subtypes, implicating TERT as a central ancestry-independent node in the pathogenic development of liver cancer." (PMID 28930164, 2017). "CUDR promotes liver cancer stem cell growth through upregulating TERT and C-Myc48." (PMID 27782152, 2016). "Our previous study shows CUDR promotes liver cancer stem cell growth through upregulating TERT." (PMID 27367027, 2016). "Importantly, liver cancer cell lines have been shown to be addicted to TERT and that malignant phenotype may be reverted by anti-TERT oligonucleotides." (PMID 36358677, 2022). "Another limitation of the present study is that the difference in Wnt/CTNNB1 mutations, apart from TERT promoter mutations, could not be investigated according to the etiology of liver cancer." (PMID 35306637, 2022). "However, it remains unclear whether TERT promoter mutation (TERT C228T) in serum cfDNA is useful for the diagnosis of liver cancer with non-viral fatty liver disease (FLD)." (PMID 35306637, 2022). "Our recent report highlighted the better performance of TERT C228T in serum cfDNA than AFP and PIVKAII in the early diagnosis of primary liver cancer in patients with non-alcoholic fatty live disease (NAFLD)." (PMID 35306637, 2022). "AUROC, sensitivity, specificity, PPV, and NPV of TERT C228T were 0.812, 63.9%, 95.2%, 95.8%, and 60.6% in predicting NAFLD-related liver cancer, respectively." (PMID 35306637, 2022). "Here we show that a combination of oncogenes that is characteristic of liver cancer (CTNNB1, TERT, MYC) induces senescence in human fibroblasts and primary hepatocytes." (PMID 34302118, 2021). "TGF-β, together with the chromatin insulator CCCTC-binding factor (CTCF), epigenetically and transcriptionally regulate tumor promoter genes, including IGF2 and TERT, in TGF-β–defective mice and in human liver cancers." (PMID 33457451, 2020). "Focal amplification on 5p15.33 (TERT) and 11q13.3 (CCND1, FGF19) was found in 7 (38.1%) and 3 (9.52%) liver cancer patients, respectively." (PMID 32458568, 2020).
liver cancer (continued). "Our previous study showed that the overexpression of H19 increases the binding of TERT to TERC and reduces the interplay between TERT with TERRA, thus enhancing the cell telomerase activity and extending the telomere length in liver cancer stem cells." (PMID 27167190, 2016). "Our results highlight the importance of serum TERT C228T for the detection of non-viral FLD-related liver cancer." (PMID 35306637, 2022). "Further study according to the etiology should be performed to investigate the difference in the rates of positive TERT C228T in precancerous stage without liver cancer." (PMID 35306637, 2022). "Multivariate analysis identified the etiology of FLD, vascular invasion, and non-cirrhosis as determinants of TERT C228T-positive liver cancer." (PMID 35306637, 2022). "In conclusion, our results highlight the importance of serum TERT C228T for the detection of non-viral FLD-related liver cancer." (PMID 35306637, 2022). "Our previous report showed the rates of positive TERT C228T were 4.8% in serum samples of NAFLD without liver cancer." (PMID 35306637, 2022). "Potential mechanisms underlying the ARID2-CTNNB1 and ARID1A-AXIN1 associations in liver cancer have not been explored in depth, perhaps because these genes are less commonly altered in HCC (~10%) than TERT or CTNNB1." (PMID 34439356, 2021). "When comparing gene expression in samples with virus integration to those without, we found that only TERT was overexpressed (fold change ≥2.0) in two liver cancer samples." (PMID 32025001, 2020). "We also analyzed the correlation between NACO3, SP1 and TERT mRNA expression in liver cancer patients in the GEO database (GEO: GSE10143), the mRNA level of SP1 was a positive correlation with the NCOA3 (R2 = 0.7367, p < 0.0001) and TERT (R2 = 0.0.401, p < 0.0001)." (PMID 33239622, 2020). "Unfortunately, our results could highlight the importance of serum TERT C228T for the detection of non-viral FLD-related liver cancer, but the superiority of TERT C228T could not be compared with AFP or with PIVKAII." (PMID 35306637, 2022). "As one limitation of the present study, we could not examine TERT C228T in the precancerous serum samples without liver cancer." (PMID 35306637, 2022). "However, it is unknown whether the rates of positive TERT C228T might be different among the three etiologies of HBV, HCV, and FLD-related liver cancer." (PMID 35306637, 2022). "However, it remains unclear whether serum TERT C228T is useful for the diagnosis of non-viral fatty liver disease (FLD)-related liver cancer, which has had an increasing trend recently." (PMID 35306637, 2022). "Anti-HCC analysis showed that GT-multi-siRNA without an extra delivery carrier could also enter Hep3B liver cancer cells to silence the GP73 and TERT genes and inhibit Hep3B cell proliferation and migration." (PMID 41471333, 2025).
colorectal cancer (57 papers, 2008 to 2025). A primary or metastatic malignant neoplasm that affects the colon or rectum. "Colorectal tumor-associated antigen-1, mesothelin tumor-associated antigen, and telomerase catalytic subunit TERT were upregulated in oxaliplatin-resistant colorectal cancer cells collected from a large number of patients treated with the drug." (PMID 34639014, 2021). "Common genetic variants of telomerase reverse transcriptase (TERT) have been associated with a wide range of cancers, including colorectal cancer (CRC) in LS." (PMID 34059744, 2021). "There is a strong association between TERT methylation and telomerase activity in some tumour types, including B-cell lymphocytic leukaemia, colorectal carcinoma, NOS and pancreatic ductal adenocarcinoma." (PMID 29751586, 2018). "Our data also suggest that associations between TERT and colorectal cancer, possibly mediated by miRNAs, involve numerous pathways other than telomerase." (PMID 27627813, 2016). "We focus on associations between miRNAs and TERT SNPs previously associated with colorectal cancer and examine miRNA expression in normal colonic mucosa tissue as well as the differential expression of miRNAs between carcinoma and normal colonic mucosa tissue." (PMID 27627813, 2016). "We have shown previously that TERT rs2853676 was associated with TL and that TL was associated with colorectal cancer." (PMID 27627813, 2016). "In the present study we aimed to determine the frequency ofhotspot TERT promoter mutations in 145 Brazilian patients,including 103 subjects with precursor lesions and 42 with colorectal carcinomas,and we associated the presence of such mutations with the patientsclinical-pathological features." (PMID 29473934, 2018). "Additionally TERT-CLPTM1L rs2853668 and TERT rs2736118 were associated with colorectal cancer risk in this study population." (PMID 27627813, 2016). "Telomerase has been recognized as a crucial predictor of overall survival in colorectal cancer patients, with those having higher TERT levels showing markedly worse survival rates compared to those with lower TERT levels." (PMID 39409990, 2024). "Taken together, we show that pKAL enhances the anticancer effect of β-Lap in HCT116-OxPt-R colorectal cancer cells through the modulation of TERT, CD44, and EGFR-mediated multiple signaling networks." (PMID 38139333, 2023). "Taken together, our results show that pKAL enhances the anticancer effect of β-Lap in HCT116 colorectal cancer cells containing OxPt-R by downregulating TERT, CD44, EGFR, and upregulated oxaliplatin resistance-related proteins." (PMID 38139333, 2023). "Perhaps more pertinently to this study, it has very recently been demonstrated that siRNA‐mediated downregulation of LRP in colorectal cancer cells, not only decreased the telomerase activity, but also decreased the TERT and phosphorylated TERT (pTERT) levels." (PMID 36579897, 2023). "For example, hsa_circ_0020397 affected cell viability, apoptosis, and invasion through sponging miR‐138 to modulate TERT and PD‐L in colorectal cancer." (PMID 35302673, 2022). "TERT participated in the early stages of colorectal cancer development through inducing COX-2 expression to influence the tumor’s stromal microenvironment." (PMID 35783272, 2022). "Hsa_circ_0020397 has been shown to regulate cell viability and invasion of colorectal cancer (CRC) cells by sponging miR-138 to promote TERT and PD-L1 expression." (PMID 33858418, 2021). "The expression of CTNNB1, its target genes, and TERT have been reported at the invasive edges of colorectal cancer." (PMID 34439356, 2021). "Functional analyses indicated that overexpression of miR-138-5p and miR-422a significantly inhibit TERT expression through interaction with TERT 3’UTR in colorectal cancer cells." (PMID 33329574, 2020).